FER1L6 (fer-1 like family member 6)
Description:
Calcium/phospholipid-binding protein which is essential for proper development of skeletal and cardiac muscle.
Synonyms: C8orfK23
Tractability: Antibody: its Gene Ontology location is reachable by antibodies, with high confidence; UniProt predicts a signal peptide or a membrane-spanning region; the Human Protein Atlas places it where antibodies can reach. PROTAC: ubiquitination databases record sites on it.
Gene: Protein-coding gene on chromosome 8 (123,851,987 to 124,120,061, forward strand). Ensembl gene ENSG00000214814.
Subcellular location: Cell membrane; Cytoplasm, perinuclear region; Golgi apparatus, trans-Golgi network; Recycling endosome
Subcellular location (Human Protein Atlas): Plasma membrane; Cytokinetic bridge; Cytosol; Mitotic spindle
Gene Ontology:
Molecular function: calcium-dependent phospholipid binding
Biological process: cardiac muscle tissue development; positive regulation of gene expression; skeletal muscle tissue development
Cellular component: plasma membrane; recycling endosome; trans-Golgi network; perinuclear region of cytoplasm; Golgi apparatus; membrane
Genetic constraint (gnomAD): Loss-of-function variants: 137 observed, 186.02 expected, observed/expected ratio (o/e) 0.74, 90% interval 0.64 to 0.85. The upper end of that interval is the gene's LOEUF score, 0.85, which puts it in group 3 of 6, group 1 being the genes least tolerant of losing a copy. Missense variants: 1,902 observed, 2,130.5 expected, observed/expected ratio (o/e) 0.89, 90% interval 0.86 to 0.93. Synonymous variants: 694 observed, 790.47 expected, observed/expected ratio (o/e) 0.88, 90% interval 0.82 to 0.94.
Homologues: Orthologues: chimpanzee FER1L6 (99% identical), macaque FER1L6 (97% identical), rabbit FER1L6 (90% identical), dog FER1L6 (90% identical), pig FER1L6 (90% identical), mouse Fer1l6 (88% identical), rat Fer1l6 (88% identical), guinea pig FER1L6 (88% identical), tropical clawed frog fer1l6 (70% identical), zebrafish fer1l6 (59% identical), Drosophila melanogaster mfr (22% identical). Paralogues in human: OTOF (49% identical), DYSF (34% identical), MYOF (33% identical), FER1L5 (28% identical).
Diseases named in the same sentence as FER1L6 in open-access papers:
FER1L6 is named in the same sentence as 6 diseases in open-access papers, as found by Europe PMC text mining. Sharing a sentence is not in itself a finding about the gene and the disease. The quoted sentences say what the papers report.
major depressive disorder (1 paper, 2020). An episode of depression lasting two or more weeks without an intervening episode of mania. "Interestingly, another of our top 20 CpG sites (cg26822318) falls in proximity to the FER1L6 gene, of which a variant (rs4870888) has been associated with suicide attempts in a meta-analysis of major depressive disorder, schizophrenia and BD." (PMID 32048126, 2020).
Miyoshi muscular dystrophy (1 paper, 2022). "Second statistically significant SNP is located in an intron of the FER1L6 gene (FER-1 like family member 6) which is associated with diseases including cerebellar ataxia type 43 and Miyoshi muscular dystrophy." (PMID 35957660, 2022).
tumor (1 paper, 2024). "We also identified three DEGs (HOXD10, IFNA1, and FER1L6) related to tumor size." (PMID 38745021, 2024). "DEG analyses revealed the genes contributing to RFS and related to SUVmax (PSG5, TFF3, SOX2, SLC5A5, and SLC5A7) and tumor size (HOXD10, IFNA1, and FER1L6)." (PMID 38745021, 2024).
FER1L6 also shares sentences with these, for which no sentence is quoted: male infertility (1 paper); prostate carcinoma (1); schizophrenia (1).